FOXP1 (forkhead box P1)
Diseases named in the same sentence as FOXP1 in open-access papers (continued):
Sharing a sentence is not in itself a finding about the gene and the disease.
MALT lymphoma (16 papers, 2006 to 2025). An indolent, extranodal type of non-Hodgkin lymphoma composed of small B-lymphocytes (centrocyte-like cells). "FOXP1 is located on the tumor suppressor locus at chromosome 3p14.1, and trisomy of chromosome 3 has been associated with increased FOXP1 expression in mucosa-associated lymphoid tissue lymphoma." (PMID 25663935, 2015). "It has also been reported that MALT lymphomas showing strong FOXP1 expression are at risk for transformation into an aggressive form of DLBCL." (PMID 24887414, 2014). "Furthermore, the results showed that decreased FOXP1 expression was correlated with the best OS in patients with MALT lymphoma but associated with the worst OS in NSCLC patients." (PMID 27457567, 2016). "FOXP1 (3p14.1) is overexpressed in a few MALT lymphomas due to its juxtaposition to the immunoglobulin heavy chain gene promoter after chromosomal translocation." (PMID 35008340, 2021). "The absence of translocations affecting the genes BCL10, MALT1, BIRC3, or FOXP1, as they are frequently seen in other types of MALT lymphomas, in six OAML analyzed by WGS is in line with published data." (PMID 32316399, 2020). "An elevated FOXP1 RNA expression level has been reported in DLBCL, activated B-cell like (ABC) subtype, and MALT lymphoma at high risk of transforming into aggressive DLBCL." (PMID 27806315, 2017). "FOXP1 is targeted by chromosome translocations in MALT lymphoma and DLBCL, wherein high-level protein expression is associated with a poor prognosis." (PMID 24887414, 2014). "For instance, FOXP1 over-expression though inhibition of apoptosis and plasma cell differentiation may contribute to the pathogenesis of MALT lymphomas." (PMID 35008340, 2021). "Chromosome 3 harbors the FOXP1 gene and has been identified as a translocation partner with the IGH gene in both DLBCL and MALT lymphomas." (PMID 40075754, 2025). "Interphase FISH showed a low frequency (7%) of FOXP1, but not MALT1 translocation in thyroid MALT lymphoma." (PMID 34021249, 2021).
gastric cancer (14 papers, 2012 to 2025). A primary or metastatic malignant neoplasm involving the stomach. "BART11 promotes chronic inflammation and carcinogenesis of nasopharyngeal and gastric cancer by inhibiting the anti-tumor effect of forkhead box p1 (FOXP1)." (PMID 36411555, 2024). "LncRNA MIR99AHG activated the FOXP1-mediated Wnt/β-catenin pathway by competing for endogenous RNA of miR-577, promoting gastric cancer." (PMID 35158722, 2022). "Studies have shown that lncRNA MIR99AHG induces EMT and inhibits apoptosis through miR577/FOXP1 axis to promote gastric cancer progression." (PMID 35528617, 2022). "Here, the authors show that EBV-encoded miRNAs EBV-miR-BART11 and EBV-miR-BART17-3p upregulate PD-L1 expression in nasopharyngeal carcinoma and gastric cancer by targeting FOXP1 and PBRM1." (PMID 35165282, 2022). "The expression levels of EBV-miR-BART11-3p, EBV-miR-BART11-5p, EBV-miR-BART17-3p, FOXP1, PBRM1, and PD-L1 were determined using samples of NPC and EBV-associated gastric carcinoma tissues by performing IHC or ISH methods." (PMID 35165282, 2022). "EBV-miR-BART11 plays a crucial role in the promotion of carcinogenesis in gastric cancer and nasopharyngeal carcinoma by inhibiting the tumor-suppressive effects of FOXP1." (PMID 28705173, 2017). "Downregulates FOXP1 and its tumor‐suppressive effect, inhibits FOXP1‐induced differentiation of TAM, promotes proliferation and inflammation‐induced carcinogenesis of gastric cancer and nasopharyngeal carcinoma." (PMID 39185567, 2025). "Specifically, FOXP1 is recruited to multiple sites within the promoter region of FBXL7 and transactivates the expression of FBXL7 in gastric cancer cells." (PMID 35906197, 2022). "FOXP1 and PBRM1 expression levels were low, while EBV-miR-BART11-3p, EBV-miR-BART11-5p, and EBV-miR-BART17-3p were highly expressed in NPC and gastric carcinoma tissues." (PMID 35165282, 2022). "Together, these results suggest that AURKA targets FOXP1 to negatively regulate the expression of FBXL7, which can in turn negatively regulate Survivin protein levels in gastric cancer cells." (PMID 28218735, 2017). "The immunotherapeutic response rate between the high and low FOXP1-expressing gastric cancer patients was not statistically significant." (PMID 40672953, 2025).
atherosclerosis (12 papers, 2019 to 2026). A disease characterized by the build-up of fatty material and calcium deposition in the arterial wall resulting in partial or complete occlusion of the arterial lumen. "In human patients with atherosclerosis and athero-susceptible endothelium of mouse models, the expression of FOXP1 was down-regulated." (PMID 35203463, 2022). "It has been reported that FOXP1 expression is remarkably downregulated in atherosclerosis and atherosclerosis-susceptible endothelial human coronary arteries and mouse arteries." (PMID 35043753, 2022). "It is worthy of note that FOXP1 expression is remarkably downregulated in atherosclerosis and atherosclerosis-susceptible endothelial human coronary arteries and mouse arteries." (PMID 35043753, 2022). "In the ApoE knockout (KO) hyperlipidemic mouse model, the loss of FoxP1 in endothelial cells promotes atherosclerosis, and endothelial FoxP1 affects the adhesion, migration, and penetration of monocytes into the vascular wall in the pathogenesis and progression of atherosclerosis." (PMID 36088337, 2022). "As atherosclerosis is one cause of large vessel disease, a major subtype of IS, there may be more associations between FOXP1 and IS." (PMID 32719717, 2020). "Here, our study offers a novel finding that FOXP1-mediated phase separation sustains the ability to delay endothelial cell senescence, thereby contributing to endothelial homeostasis and anti-atherosclerosis." (PMID 41355963, 2026). "FOXP1 is identified as a core transcription factor, driven by super-enhancers, which delays endothelial cell senescence and inhibits atherosclerosis." (PMID 41355963, 2026). "This study reveals a novel role for lactate in instigating vascular inflammation during atherosclerosis by coordinating the MCT1/NADH/CtBP1‐dependent transrepressive activity of FOXP1 in ECs." (PMID 39949978, 2025). "For instance, simvastatin upregulates KLF2 expression in ECs, enhancing Foxp1 activity to suppress vascular inflammation and inhibit atherosclerosis progression." (PMID 41373858, 2025). "In this study, ox-LDL-induced murine macrophage cell line RAW264.7 was used to explore the role of FOXP1 in inflammation and lipid accumulation during atherosclerosis progression." (PMID 35043753, 2022). "At present, studies on FoxP1 in cardiac function have mainly focused on myocardial cell proliferation and atherosclerosis." (PMID 36088337, 2022). "In addition, en face analyses of atherosclerotic senescent and plaque areas in the whole aortas and the aortic roots revealed that FOXP1 protected against endothelial senescence and atherosclerosis." (PMID 41355963, 2026). "In this study, we characterized the epigenomic landscape of endothelial cell senescence and found that the core transcription factor FOXP1 regulated by super-enhancers can delay endothelial cell senescence, alleviate endothelial dysfunction and atherosclerosis." (PMID 41355963, 2026). "In conclusion, we characterized the genomic landscape of endothelial cell senescence and revealed the critical role of the super-enhancer-driven core transcription factor FOXP1 in delaying endothelial cell senescence, alleviating endothelial dysfunction and reducing atherosclerosis." (PMID 41355963, 2026). "In light of studies showing that FOXP1 can transcriptionally repress the NLRP3 inflammasome and inhibit the development of atherosclerosis, we hypothesized that CtBP1 might interact with FOXP1 to modulate VCAM‐1 and ICAM‐1 gene transcription." (PMID 39949978, 2025). "Further research is needed to determine whether these events occur in the context of atherosclerosis and whether FOXP1 can synergize with NF‐κB to regulate endothelial inflammation." (PMID 39949978, 2025). "Endothelial Foxp1 inhibits atherosclerosis by regulating Nlrp3 inflammasome activation." (PMID 38694921, 2024). "FOXP1 knockdown contributes to the development of atherosclerosis in a mouse model." (PMID 35043753, 2022).
atherosclerosis (continued). "In addition, FOXP1 has a great impact on the occurrence and development of some immune diseases, such as atherosclerosis." (PMID 35173708, 2021). "Furthermore, miR-206 may be a protective factor in atherosclerosis by inhibiting the expression of FOXP1, which is involved in controlling the proliferation of VSMCs." (PMID 31011482, 2019). "The clinical evidences support the potential role of FOXP1 and SESN3 as protective factors against atherosclerosis." (PMID 41355963, 2026). "FOXP1 transrepresses NLRP3 inflammasome components, and its targeted deletion in ECs intensifies atherosclerosis in Apoe−/− mice." (PMID 39949978, 2025). "Inhibiting MCT1 reduces lactate‐induced vascular inflammation and atherosclerosis in Apoe−/− mice, suggesting that the lactate‐dependent NADH/CtBP/FOXP1 pathway is a potential therapeutic target." (PMID 39949978, 2025). "However, further investigation is required to understand the impact of FOXP1 LLPS disruption on endothelial cell senescence and atherosclerosis in vivo, as well as the peptide targeting FOXP1 LLPS." (PMID 41355963, 2026). "Moreover, the expression of FOXP1 was positively correlated with SESN3 and negatively correlated with CDKN2A, MMP9, and ICAM1 in human atherosclerosis plaques." (PMID 41355963, 2026). "Thus, suggesting the role of shear stress in down-regulation of ECs’ Foxp1 (via KLF2 repression) and inflammasome activation, promoting atherosclerosis." (PMID 35203463, 2022). "Accordingly, FOXP1 and SESN1 might be used as promising targets for treatment of atherosclerosis." (PMID 35043753, 2022).
cognitive disorder (11 papers, 2012 to 2025). A disease affects cognitive processes. "Recently, individuals with FOXP1 loss-of-function or mutation of the gene revealed high cognitive impairment, which is associated with mitochondrial dysfunction and oxidative stress, GI dysfunction, severe language impairment and brain development dysfunction." (PMID 41156002, 2025). "Individuals with FOXP1 loss-of-function or mutation of the gene revealed high cognitive impairment." (PMID 41156002, 2025). "Mutations in FOXP1 gene have been found in various development-related cognitive disorders." (PMID 26010426, 2015). "Related FOX transcription factors, such as FOXP1, have also been implicated in cognitive disorders." (PMID 25309332, 2014). "However, mutations in FOXP1 result in a broad spectrum of cognitive impairments in patients including severe intellectual disability, gross motor delay and autism spectrum disorder." (PMID 25309332, 2014). "Disease-causing variants in both FOXP1 and FOXP2 are relatively rare, but play a significant role in the pathology of cognitive diseases." (PMID 22736078, 2012). "In the past, members of the FOXP subfamily have been implicated in various human diseases, but only FOXP1 and FOXP2 have been linked to cognitive disorders so far." (PMID 22736078, 2012). "Autistic individuals with LoF variants in the four moderate-risk genes (NAV3, ITSN1, SCAF1 and HNRNPUL2; n = 95) have less cognitive impairment than 129 autistic individuals with LoF variants in highly penetrant genes (CHD8, SCN2A, ADNP, FOXP1 and SHANK3) (59% vs 88%, P = 1.9 × 10−6)." (PMID 35982159, 2022). "In conclusion, we provide evidence that a disrupted mitochondrial network and the resulting oxidative stress in the hippocampus contribute to the altered learning and cognitive impairment in Foxp1+/− mice, suggesting that similar alterations also play a major role in patients with FOXP1 syndrome." (PMID 35052467, 2022). "The phenotypic spectra of FOXP1 and FOXP2 disruptions suggest that these two closely related transcription factors are involved in both shared and distinct neurodevelopmental pathways underlying cognitive diseases through the regulation of common and exclusive targets." (PMID 22736078, 2012). "In the last 2 years, evidence has emerged that implicates FOXP1 (OMIM 605515), the closest relative of FOXP2 (64 % total protein sequence identity, 89 % in the forkhead domain), in the pathology of human cognitive disorders, which involve language impairment." (PMID 22736078, 2012). "Linguistic processing defects have not been found in FOXP1 patients and, although speech delay is sometimes seen, this is thought to be more related to general cognitive impairments and motor problems, rather than a speech/language specific effect." (PMID 25309332, 2014). "The findings discussed in this review show that FOXP1 and FOXP2 may provide crucial insight into the molecular pathways involved in human cognitive diseases." (PMID 22736078, 2012).
schizophrenia (11 papers, 2012 to 2026). A major psychotic disorder characterized by abnormalities in the perception or expression of reality. "FOXP1 (Forkhead-box protein P1) is a crucial transcription factor in neural development and is associated with schizophrenia (SCZ)." (PMID 41324486, 2026). "Enhancers from schizophrenia GWAS regions were found to interact with the promoters of a number of genes (DRD2, GRIN2A, CACNA1C, and FOXP1), which have previously been unambiguously linked to schizophrenia." (PMID 31963710, 2020). "The gain of power is due to multiple small independent association signals at these loci (e.g. the THRB and FOXP1 loci for schizophrenia)." (PMID 27604177, 2016). "For instance, the expression level of FOXP1 was significantly greater (two-sided P = 3.41 × 10−17) in brain regions exhibiting ECM alterations in schizophrenia." (PMID 38491019, 2024). "Particularly interesting are SF3B1, DLG2 and FOXP1 because of the strong association for the SF3B1 in the PGC meta-analysis and the previous evidence implicating DLG2 and FOXP1 in schizophrenia and other neurodevelopmental disorders." (PMID 26460480, 2015). "Furthermore, our transcriptome analysis identified significant genes, including FOXP1 and CHST8, providing insights into the molecular mechanisms underlying ECM changes in schizophrenia." (PMID 38491019, 2024). "This list also contains the FOXP1 and FOXP2 genes, which are required for development of speech and language in humans and interact with CNTNAP2, a member of the 47-gene list which is in the neurexin family of genes having known association with schizophrenia." (PMID 36711134, 2022). "While ANK3 has previously been implicated in bipolar disorder and schizophrenia, secondary CNV analysis of FOXP1 and ANK3 in 19,566 patients with ASD revealed a significant CNV burden for FOXP1, but not ANK3." (PMID 22736078, 2012).
osteosarcoma (10 papers, 2019 to 2024). A usually aggressive malignant bone-forming mesenchymal neoplasm, predominantly affecting adolescents and young adults. "Altogether, downregulation of lncRNA HOXA-AS3 reduced wound healing via miR-218-5p and FOXP1 in osteosarcoma cells." (PMID 39019995, 2024). "Taken together, downregulation of lncRNA HOXA-AS3 reduced colony formation via miR-218-5p and FOXP1 in osteosarcoma cells." (PMID 39019995, 2024). "In conclusion, lncRNA HOXA-AS3 regulated the expression of FOXP1 via sponging miR-218-5p, which led to promotion of colony formation, migration and invasion in osteosarcoma." (PMID 39019995, 2024). "We found that lncRNA HOXA-AS3 facilitates cell proliferation and invasion via targeting miR-218-5p/FOXP1 axis in osteosarcoma." (PMID 39019995, 2024). "FOXP1 has been reported to drive osteosarcoma development via inhibition of p21, retinoblastoma protein (RB) transcription and inactivation of p5337." (PMID 39019995, 2024). "A considerable body of evidence indicates that FOXP1 has an important regulatory effect on tumor progression, such as osteosarcoma, follicular lymphoma and colorectal cancer." (PMID 35043753, 2022). "Furthermore, our study demonstrated that lncRNA HOXA-AS3 enhanced tumor progression via targeting miR-218-5p/FOXP1 in osteosarcoma." (PMID 39019995, 2024). "Similarly, overexpression of FOXP1 also rescued sh-HOXA-AS3-mediated suppression of cell invasive ability in osteosarcoma cells." (PMID 39019995, 2024). "Wound healing assay was performed to measure whether inhibition of lncRNA HOXA-AS3 regulates cell migration via regulation of miR-218-5p and FOXP1 in osteosarcoma cells." (PMID 39019995, 2024). "Furthermore, pcDNA FOXP1 transfection abolished sh-HOXA-AS3-involved suppression of wound healing in osteosarcoma cells." (PMID 39019995, 2024). "Hence, silencing of lncRNA HOXA-AS3 reduced cell invasive ability in part via miR-218-5p and FOXP1 in osteosarcoma cells." (PMID 39019995, 2024). "Likewise, overexpression of FOXP1 by pcDNA FOXP1 transfection abrogated sh-HOXA-AS3-induced inhibition of colony formation in osteosarcoma cells." (PMID 39019995, 2024). "ERK/JNK and c‐JUN/c‐FOS, as upstream activators of FOXP1, drive osteosarcoma development." (PMID 36772869, 2023). "circRNA is crucial in promoting tumor angiogenesis, and we hypothesize that circ FOXP1 played role in osteosarcoma angiogenesis." (PMID 34637672, 2021). "Hence, lncRNA HOXA-AS3 could regulate FOXP1 in osteosarcoma cells." (PMID 39019995, 2024). "To further study the effect of circFOXP1 on the angiogenesis in osteosarcoma, we obviously inhibited circFOXP1 expression in U2OS and MG-63 cells treated with a lentivirus-based shRNA targeting FOXP1." (PMID 34637672, 2021). "Likewise, miR-181d-5p, miR-374b-5p, miR-122, miR-150 and miR-504 act as a tumor suppressor by inhibition of FOXP1, while miR-376a and miR-139 work as a tumor suppressor via inhibition of FOXP2 in lymphoma and osteosarcoma." (PMID 31815635, 2019).
renal cell carcinoma (10 papers, 2014 to 2024). "FOXP1 has been found to be abnormally expressed in tumors such as renal cell carcinoma and endometrial cancer." (PMID 37663229, 2023). "For instance, research has demonstrated that ZNF263 interacts with two splice sites (P3 and P4) on the FOXP1 promoter, thereby regulating the expression of circFOXP1 in renal cell carcinoma (RCC) cells, which promotes RCC cell proliferation, migration, invasion, and the Warburg effect." (PMID 39606233, 2024).